CASP8 (caspase 8)
Diseases named in the same sentence as CASP8 in open-access papers (continued):
Sharing a sentence is not in itself a finding about the gene and the disease.
tumor (continued). "Intracellular levels of pro- and antiapoptotic factors such as cFLIP, XIAP, BCL-2 family members, and DISC formation and caspase 8 activity have been reported to regulate cell sensitivity to TRAIL-induced programmed cell death in both tumour and normal cells." (PMID 15846298, 2005). "CASP8 methylation was detected in 36% of SLIT2 methylated and 41% SLIT2 unmethylated tumours (P=1.0)." (PMID 14735202, 2004). "In tumours with SLIT2 methylation, CASP8 and RASSF1A were methylated in 43% (six out of 14) and 36% (five out of 14), respectively." (PMID 14735202, 2004). "Activation of caspase-8 by TRAIL or IR, therefore, seems to be a common reaction pattern in a variety of different tumour types, including RCCs." (PMID 12771998, 2003). "It was found that it regulated cellular responses along with apoptotic mechanisms in cells without developing resistance in suppressing tumor growth by making changes on Atf2, Casp8, Bcl2 and Irf5 genes and proteins." (PMID 41656578, 2026). "Second, the hub-gene signature captures both oncogenic and tumor-suppressive targets (such as PTEN and CASP8), and the balance between these components may influence the overall prognostic trend." (PMID 41596512, 2026). "The expression and functional status of key molecules within the PANoptosome, such as ZBP1, RIPK1, RIPK3, CASP8, and ASC, may influence tumor viability and immune detection." (PMID 40422233, 2025). "Additionally, caspase-3 interacts with other proteins, such as caspase-8 and HLJ1, coordinating apoptosis and influencing tumor progression." (PMID 40149995, 2025). "TRAIL/TNFSF10 is a member of the tumor necrosis factor (TNF) death ligand family that selectively initiates extrinsic apoptosis in caspase-8-dependent tumor cells without affecting normal cells." (PMID 40230861, 2025). "Specifically, ScA activates caspase-8, leading to apoptotic cell death even in tumors lacking caspase-8, in part through effects on the tumor vasculature." (PMID 40559642, 2025). "In vivo, a single low dose of ScA in a mouse model inhibited the growth of both caspase-8-positive and -negative tumors by targeting the tumor blood vessels." (PMID 40559642, 2025). "In addition, oxidative stress activates CASP8 via the Fas and FasL pathway, ultimately leading to the assembly of ZBP1-CASP8 PANoptosome and PANoptosis of B16 tumor cells." (PMID 40739587, 2025). "A therapeutic target may be to sensitize tumor cells with agents that induce PANoptosis through activation of ZBP1, CASP8, RIPK3, or other key components." (PMID 40422233, 2025). "Despite these insights in other contexts, how absent caspase 8 expression shapes NE tumor development, biology and progression in SCLC has remained unexplored." (PMID 41413044, 2025). "Caspase-8 is therefore essential for the immune response, B and T lymphocyte activation, and macrophage differentiation and polarization in the TME, in addition to the primary tumor cells." (PMID 40674382, 2025). "In tumor cells, TNF-α triggers caspase-8, leading to GSDMC cleavage at the D365 amino acid." (PMID 38304430, 2024). "This research not only elucidates a pyroptotic pathway associated with metabolites but also unveils a previously unreported central pathway extending from ROS-triggered DR6 endocytosis to caspase-8-mediated cleavage of GSDMC, suggesting potential clinical applications in tumor therapy." (PMID 38877579, 2024). "We conclude that Casp8 deletion reduces the time to tumor formation rather than the type of tumor that is formed." (PMID 39625985, 2024). "We assessed the expression of apoptosis-related proteins (caspase-3, caspase-8, and caspase-9) in tumours obtained from nude mice treated with or without ART using immunohistochemistry." (PMID 38773551, 2024).
tumor (continued). "We first compared the differences in protein expression of BAX, CASP1, CASP8 and PYCARD in renal clear cells by CPTAC database, and the results showed that the protein levels of BAX, CASP1, CASP8 and PYCARD were significantly higher than those in normal tissues in tumor cells." (PMID 38439022, 2024). "In addition, CASP8 was found to regulate YEATS2 in HCC, highlighting a potential pathway in tumor progression." (PMID 38186679, 2023). "TNFR1, caspase-8, FADD, RIPK1, the LUBAC components, TRAF2 and cIAP1 have all been identified in genome-wide Crispr/Cas9 screens as important factors involved in the control of tumor development by CD8+ T cells and NK cells." (PMID 38020877, 2023). "The top-scoring genes altered in the four gene sets included many genes associated with cell apoptosis and DNA damage, such as GADD45A, DDIT3, BAX, CASP1, CASP8, ATM, and FANCD2, demonstrating that diminishment of RAD51 contributes to the tumor suppressive effect." (PMID 37175611, 2023). "In addition, the level of the mRNA gene expression of the key protein of the extrinsic apoptosis pathway CASP8 was also increased in tumor tissue injected with CIMVs-TRAIL, indicating the activation of TRAIL-mediated apoptosis in tumor cells." (PMID 36661524, 2023). "Activation of CASP8 and, to a lesser extent CASP3, was found in keratinised areas of the tumours." (PMID 37443405, 2023). "The newly emerging non-canonical roles of Caspase-8 have challenged the dogma that identifies the cysteine-aspartic protease as a classic tumor suppressor due to its role in programmed cell death." (PMID 37444381, 2023). "Activated caspase 8 detection kit also confirmed the data (n = 3, **** p < 0.0001); number of alive MCF-7 after cultivation with CIMVs-TRAIL was 83.4 ± 0.9%, native CIMVs—89.7 ± 0.7%, CIMVs-BFP—90.4 ± 0.6%, native tumor cells—91.1 ± 0.6%." (PMID 36661524, 2023). "However, caspase-8 prevented ZBP1-RIPK3-MLKL-mediated tumor necroptosis after radiotherapy and rendered tumor cells resistant to treatment." (PMID 37771585, 2023). "Since Casp8 knockout significantly reduced CD8+ T cell infiltration and the inflammatory response in tumor cells, we speculated that the B16-C8KO clone was resistant to ICB immunotherapy." (PMID 36635765, 2023). "In addition, caspase 8 cleaves GSDMC to create GSDMC‐NT, which triggers tumor necrosis by forcing cancer cells to undergo pyroptosis instead of apoptosis." (PMID 37752941, 2023). "In conventional 2D cultures of tumor cells, sustained ER stress has been shown to activate the extrinsic apoptotic pathway through PERK pathway-mediated upregulation of TRAIL-R2/DR5 expression that induces the activation of caspase-8 at an intracellular DISC." (PMID 35115486, 2022). "We, therefore, speculated that the Rnf31 knock-out sensitizes tumor cells to TNF-mediated apoptosis either indirectly, by abrogating NFκB pro-survival signaling, or directly, by facilitating caspase 8 cleavage." (PMID 35379808, 2022). "CDK9 detection was significantly increased (p = 0.014) in tumors with high caspase-8 expression but did not display a correlation with age, T-stage, N- and M-stage, tumor grading and FIGO category." (PMID 36428594, 2022).
tumor (continued). "The heatmap showed that a decreased CASP8 expression was associated with lymph node involvement in BLCA (p < 0.05) but was not related to the T and M scores in tumor staging." (PMID 35928267, 2022). "Following caspase-8 activation in tumor cells, GSDMC has been found to mediate tumor necrosis." (PMID 35992142, 2022). "Moreover, a decrease in the levels of RELA, NOD1, CASP8, BCL2L1, ELK1, and IKBKB was identified in poorly differentiated tumours compared to moderately differentiated tumours." (PMID 36433652, 2022). "CASP8, CASP6, GSDME, NOD1, and GPX4 were significantly upregulated in tumor tissues compared to the normal tissues, whereas IL6, IL1B, NLRP3, and NLRC4 were downregulated, suggesting that pyroptosis-related genes play important roles in tumor progression and prognosis." (PMID 35559014, 2022). "Furthermore, we also examined mice tumor tissues and found that Eeq also promoted DR5 and E-cadherin while inhibiting expression of caspase 8 (full length), surviving, and N-cadherin in vivo." (PMID 36034825, 2022). "The recent evidence has been reported that supports the role of caspase-8 in tumor cell migration under the nonapoptotic condition." (PMID 34367939, 2021). "CASP8, RASSF1 were the most frequently methylated genes in all tumor samples." (PMID 34771655, 2021). "Interestingly, the current study revealed that TNF α - activated caspase-8 switched apoptosis to pyroptosis in the presence of hypoxia-activated GSDMC and nPD-L1, leading to tumor necrosis in hypoxic regions." (PMID 35047554, 2021). "Collectively, this study not only identifies the key node protein (DR6), pyroptosis initiator (caspase-8), and executor (GSDMC) in the α-KG-induced pyroptotic pathway but also provides an important research direction for clinical tumor treatment via pyroptosis induction." (PMID 34012073, 2021). "Due to the variety of apoptotic and non-apoptotic functions, caspase-8 is a crucial factor in tumorigenesis, tumor progression, and therapy response." (PMID 33026575, 2021). "Similar to the previous reporting the driver genes in CC, FBXW7, EP300, CASP8 and FAT1(10%, 20%, 10% and 10% of tumor, respectively) were also identified in our cohort with a low frequency, which may result from a small sample size in our cohort." (PMID 34221990, 2021). "Thereby it is reasonable that the combination of AQP1 with RIPK1 at D324 sequence is an obligatory step for TNBC to facilitate the recruitment of caspase-8, aggravate the cleavage of RIPK1, sequester RIPK1 in a quiescent form, and finally unleash tumor progression." (PMID 33980862, 2021). "Moreover, in an explorative response prediction model, the combination of protein markers (CXCL9, CXCL10, IL-15, CASP8, and ADA) resulted in higher accuracy in predicting response than tumor PD-L1 expression or each protein assayed individually." (PMID 34206510, 2021). "To explore the roles of Casp8 in tumor progression with or without a complete immune system, we screened murine B16 cells after Casp8 knockdown and injected them s.c. into mice." (PMID 33934451, 2021). "MOC1-CASP8 KO cells engineered for DOX-inducible expression of murine versions of either WT caspase-8 or the D303G mutant were inoculated into the flanks of wild-type C57BL/6 mice and tumor-bearing mice were randomized to receive either DOX (in drinking water) or no DOX." (PMID 34362880, 2021). "Chemotherapy treatment with or without birinapant decreased tumor growth rate of high-Caspase 8 xenografts by 1/3 to 1/2 after 8 weeks (*p < 0.05 compared to vehicle)." (PMID 34088893, 2021).
tumor (continued). "Proto-oncogenes are those genes that are involved in cell growth and proliferation, with potential examples including the ATM, FGFR2, FN1, IGF1, MAP3K, MMP7, and RHOC genes, while the CASP8 and LSP1 genes have been reported to possess tumor-suppressive properties in certain types of cancer." (PMID 33112566, 2020). "Our result is similar to previous studies not included in this analysis, which have found CASP8 to be methylated in 14%–62% of NB tumor specimens." (PMID 33381579, 2020). "Apoptosis-related DEGs, including CASP8 and TNFSF10, were overexpressed in OC3 tumor cells, which might explain the tumor growth retardation of OC3 xenografts." (PMID 32605311, 2020). "When tumor lysates were probed for cleaved Caspase-8, tumors from TM treated mice demonstrated a trend towards increased cleaved Caspase-8 but differences were not significant." (PMID 32085796, 2020). "Secondly, tumor cells can sabotage apoptotic signal in many different levels by increasing cFLIP, reducing FADD expression, and attenuating caspase-8 expression." (PMID 32212814, 2020). "After activation, CTL expresses FasL and TNF-α, binds to the Fas and TNFR1 on the surface of tumor cells, and generates FADD, which will conduct the apoptosis signal into the cell and perform CASP8 proteolytic activation, thus initiating the apoptosis process of tumor cells." (PMID 31905767, 2019). "The allosteric non-neuregulin competing modulator 9F7-F11, sensitizes tumor cells to DR5/caspase-8-mediated apoptosis through ITCH-dependent downregulation of c-FLIP." (PMID 31443721, 2019). "In addition, epigenetic changes play a role in TRAIL resistance via theregulation of caspase-8 gene expression, and DNA methylation can restore apoptosisin TRAIL-resistant tumor cells." (PMID 31444476, 2019). "Phospho T273 caspase 8 detection was significantly (p = 0.031) associated with T stage, but not with age, N and M stage, FIGO category, and tumor grading." (PMID 31475104, 2019). "Treatment of CTLA-4 expressing tumor cell lines with recombinant forms of the CTLA-4 ligands CD80 and CD86 induced caspase-8-dependent apoptosis and the level of apoptotic tumor cells was reduced by soluble CTLA-4 and anti-CTLA-4 single-chain variable fragment antibodies." (PMID 29682176, 2018). "By reviewing the list of genes without impact like ERBB3, CASP8, RAF1 and KRAS (FaDu) as well as KEAP1, KRAS, RAF1 and FANCD2 (SAS), one finds tumor drivers ranked among the top 100 mutated genes in HNSCC." (PMID 29719593, 2018). "To provide evidence that the TNF/death receptor pathways are activated in the regressing tumor, we conducted IHC analysis for cleaved caspase 8 in regressing and non-regressing tumors." (PMID 30323292, 2018). "Western blot analysis of cleaved caspase-8 and caspase 3/7 activity assays revealed that the pre-treatment with Cetuximab or ENb were comparable and significantly reduced ENb-TRAIL induced apoptosis in all the three tumor lines tested." (PMID 28572590, 2017). "Finally, we detected Vps34, Beclin 1, LC3 II, p62/SQSTM1, unprenylated Rab7, prenylated Rab7, caspase 8, caspase 3 and PARP proteins in xenografted tumor samples." (PMID 28147319, 2017). "Moreover, expression of the cleaved caspase-8, caspase-9 and PARP in tumor sections were also increased by AZOX in the xenograft mice model." (PMID 28567017, 2017). "A few TMA cores were not assessed due to insufficient tumour or the core being missing, a total number of 1421 cases for caspase-3, and 1402 cases for caspase-8 were assessed." (PMID 27798717, 2017). "Herein, overexpression of BM742401 resulted in the activation of Caspase 9 and Caspase 3, but not Caspase 8, showing that the tumor suppressive function of BM742401 in CLL was mediated by activation of intrinsic apoptosis pathway." (PMID 27689399, 2016). "Besides, 4EGI-1 induced apoptosis in NPC cells through the DR5-caspase-8 axis on 4E-BP1 and eIF4E dephosphorylation exerting positive influence on their anti-tumor activities." (PMID 26942880, 2016).
tumor (continued). "Therefore, we employed Western blot to assess the expression levels of apoptotic proteins involved in the extrinsic (caspase-8) and the intrinsic (caspase-9 and PARP) pathways, in the tumor tissues at 24 h after cryoablation." (PMID 24818132, 2014). "Interestingly, a tumor promoter such as EGF induces caspase-8 ubiquitination and reduces half-life of caspase-8." (PMID 23936765, 2013). "Western blot analysis of tumor tissue lysates also revealed that the expression levels of DR5, caspase-3 and caspase-8 were significantly up-regulated in the group treated with the combination therapy and to a higher extent than the groups treated with either DHA or Apo2L/TRAIL alone." (PMID 22666346, 2012). "Moreover, epigenetic silencing of caspase-8 has been identified as a resistance mechanism in response to death receptor stimulation in a small proportion of RMS cell lines and primary tumor specimens." (PMID 22294874, 2012). "A possible explanation for this discrepancy is that while it has been reported that Bet A activates both caspase-8 and caspase-3 in different tumor cells no Bet A-mediated activation of caspase-1 has been described." (PMID 23166834, 2012). "Altered caspase function can also be a consequence of modified expression of their specific inhibitors, as an example cFLIPs that competes with caspase 8 for FADD binding, thus preventing its activation, is often elevated in tumours, while its down-regulation can sensitize tumour cells to therapy." (PMID 22683550, 2012). "Hypermethylation of DcR1 (28.4%), but not death receptors (DR4 and DR5) and other TRAIL signalling-related genes (APAF1, CASP8 and DcR2) in our study indicates the potential use of recombinant TRAIL or TRAIL receptor agonistic monoclonal antibodies as selective anti-tumour therapy in CCA." (PMID 21448164, 2011). "In the current study we observed in epithelial, endothelial, myeloid and tumor cells, that lack of caspase-8 exhibited a disrupted pattern of cellular differentiation/senescence." (PMID 19924290, 2009). "It was shown previously that in some tumor cells, only the receptor-independent mitochondrial pathway is activated during hypoxia without caspase-8 involvement." (PMID 15613236, 2004). "Network pharmacology prioritized STAT3, HSP90AA1, CASP3, CASP8, and SRC as core therapeutic targets, with molecular docking confirming stable interactions between these two metabolites and targets, highlighting their potential in managing infections, neoplasms, and metabolic disorders." (PMID 41295287, 2025). "Accordingly, in our clinical cases, high CASP8 levels might not restrict tumor cell proliferation, but potentially reduce TNBC cell migration and metastatic spread, resulting in improved RFS and DMFS." (PMID 40806359, 2025). "Since TRAIL-R2/FADD/pro-caspase-8 and cFLIP colocalize in intracellular membrane compartments even in the absence of TRAIL, cFLIPL downregulation in glutamine-dependent tumor cells could facilitate TRAIL-R2/DR5 aggregation and subsequent NF-kB activation, leading to IL-8 induction." (PMID 40683891, 2025). "Through unknown mechanisms, heat shock protein 90 (USP90), histone deacetylase 2 (HDAC2), Cdk5 and Abl enzyme substrate 1 (CABLES1), the pituitary tumor apoptosis gene (PTAG), thrombospondin-1 (TSP-1), and caspase-8 (CASP-8) are also involved in the tumorigenesis of corticotrophinomas." (PMID 40299639, 2025). "Cellular RIPK1-caspase-8-dependent apoptosis was enhanced by the use of SIRT1 inhibitors, suggesting that RIPK1 may promote apoptosis upon acetylation, thus affecting the biological behavior of tumor cells and influencing tumor development." (PMID 40305291, 2025). "The observed upregulation of caspase-8 in AC-AFPK-IsCT1–cisplatin-treated cells suggests that the extrinsic pathway may also be involved in the observed cytotoxicity, which might be of interest in tumor cells resistant to intrinsic pathway activation alone." (PMID 40572557, 2025).